CCL4 (C-C motif chemokine ligand 4)
Diseases named in the same sentence as CCL4 in open-access papers (continued):
Sharing a sentence is not in itself a finding about the gene and the disease.
tumor (continued). "In this study, we concluded that low tumor purity in the CCL4 high groups might induce immunosuppressive TME, which contributes to antitumor immunity inhibition, activated immune checkpoint accumulation and a poor prognosis." (PMID 34900664, 2021). "Furthermore, we show that local chemokine delivery triggers directed CTL movement through dense tumour tissue in vivo, and sustained secretion of CCL3 and CCL4 from tumours promotes CTL recruitment." (PMID 33046212, 2020). "Interestingly, we observed that patients with high lymphocytic tumor infiltration showed elevated serum CCL4 (p < 0.05), when compared to those with low infiltration." (PMID 33202734, 2020). "Likewise, we found that WPS smoking can augment CCL4 expression resulting in enhanced inflammatory response, thus promoting tumor development and progression." (PMID 32961854, 2020). "CCL4 was also elevated in patients with high tumor lymphocyte infiltration." (PMID 33202734, 2020). "We speculate that memory T cells recruited to the tumor microenvironment by sensing the tumor antigens trigger a feedforward loop, which is composed of increased CCL4, recruited CD103+DC, and T cell infiltration." (PMID 32194569, 2020). "CCL4 also induces the recruitment of Treg to the tumor niche, as shown in melanoma." (PMID 33076281, 2020). "Whether MIF-dependent CCL4 expression in TANs has pro- or anti-tumorigenic effects likely depends on which immune cells infiltrate and how the tumor microenvironment specifically activates these cells." (PMID 33324425, 2020). "Immunochemotherapy with CBDCA and anti-PD-1 antibodies before surgery present sustainable protection against secondary tumors by increasing CCL4 expression in the tumor and subsequently CD103+DC and CD8+ T cells infiltration in the tumor microenvironment in mouse TNBC models." (PMID 32194569, 2020). "In addition, CCL3 and CCL4 cause the recruitment of CAF via CCR5, which is of great importance for the functioning of a tumor and the initial stages of metastatic niche formation in bones." (PMID 33076281, 2020). "We next established an in vivo model to investigate if CCL3/CCL4-secretion influences endogenous leukocyte recruitment to tumours engrafted in mice, and showed that CCL3/CCL4-secreting tumours consistently recruit more endogenous NK cells than contralateral control tumours." (PMID 33046212, 2020). "Tumor-intrinsic upregulation of β-catenin signaling induces down-regulation of the chemoattractants CCL4 and CCL5 in both mice and humans, and is associated with reduced cDC1 and CD8+ T cell infiltration, increased tumor growth, and resistance to anti-PD1 therapy." (PMID 32121071, 2020). "Indeed, detection of CD8 transcripts and BATF3 and CCL4 expression within the tumor area inversely correlated with WNT7B expression." (PMID 31921125, 2019). "As with previous research showing that LEC proliferation, migration and tube formation generates new lymphatic vessels essential for tumor lymphangiogenesis, we found that incubating LECs for 24 h with CM from CCL4-treated OSCC cells dramatically promoted LEC tube formation and migration." (PMID 29599774, 2018). "Some tumors are even able to hamper the recruitment of cDC1s, by downregulating CCL4 signaling upon constitutively active β-catenin signaling and thereby hamper priming and accumulation of tumor-infiltrating T-cells, indicating the importance of endogenous DCs for initiating anti-tumor immunity." (PMID 30559743, 2018). "More appropriate tumor implantation models are needed to investigate the role of CCL4 in OSCC." (PMID 29599774, 2018). "Other chemokines such as CCL2, CCL3, CCL4 promote tumour invasion and metastases." (PMID 29719625, 2018). "In vivo studies showed that CCL4 increased tumor volume and angiogenesis." (PMID 28404909, 2017). "IFNγ and CCL4 are known to play critical roles in tumor progression." (PMID 28512255, 2017).
tumor (continued). "In both the in vitro tumor spheres and the in vivo murine model, there was a significant increase in the factors associated with M1 macrophage polarization, such as CCR5-binding chemokines (CCL3, CCL4, and CCL5), interleukins (IL-6 and IL-1β), and TNF-α." (PMID 28670313, 2017). "This may require more detailed experimental study in the future regarding the mechanisms and clinical significance about this ERβ-regulated CCL4 in the RCC tumor microenvironment." (PMID 26587829, 2015). "Furthermore, the chemokines CCL3 and CCL4 production from tumor cells were also found to be attenuated by ibrutinib treatment." (PMID 24693884, 2014). "Collectively, these findings suggest that elevated CCL4 production in tumor lesions induced by EBL is associated with monocyte recruitment and the accumulation of phenotypically altered macrophages, highlighting a chemokine-driven remodeling of the tumor immune microenvironment." (PMID 42158858, 2026). "In addition, the IT L1 peptide/polyI:C-treated mice displayed an increase in CXCL10, CCL2, CCL3 and CCL4 and GM-CSF in the tumor lysate which could be involved in the recruitment, retention and maturation of myeloid and lymphoid cells in the tumor." (PMID 40280970, 2025). "Furthermore, tumor cells express chemokine CCL4 to recruit circulating Tregs into tumor sites." (PMID 41463331, 2025). "Furthermore, high levels of CXCL10, IL-9, and CCL4 were associated with significantly higher numbers of T cells, especially for CTL with direct contact to tumor cells, whereas for VEGF the opposite effect was observed in the tumor stroma." (PMID 40497965, 2025). "At the cellular level, the nano-vaccine could cause tumor cells ICD, capture the release TAAs for better internalization into DC cells, and realize the self-activation of DZ for β-catenin suppression to promote excretion of CCL4." (PMID 36157510, 2022). "In addition to reduced tumor growth, EVT801 decreased tumor hypoxia, favored sustained tumor blood vessel homogenization (i.e., leaving fewer and overall larger vessels), and reduced important immunosuppressive cytokines (CCL4, CCL5) and myeloid-derived suppressor cells (MDSC) in circulation." (PMID 36970050, 2022). "Intratumoral delivery of chemokines (such as GM-CSF and CCL4) has also been explored to recruit DCs, but the delivery systems are complicated for keeping the activity and local release of chemokines, and transient recruitment DCs cannot effectively present tumor antigen." (PMID 36157510, 2022). "Therefore, increased ccl4 expression increases tumor invasion and migration." (PMID 35463731, 2022). "Melanoma cells secrete CCL4, which attracts conventional DC type 1 (cDC1) and can be blocked by β-catenin signaling, indicating that the inhibition of tumor DC recruitment may be a dominant mechanism in tumor intrinsic β-catenin activation." (PMID 34063848, 2021). "CCL4 may be the key molecule functioning in immune cell infiltration in the hot tumor subtype." (PMID 33777927, 2021). "Moreover, immunofluorescence results showed that CCL4 level was positively correlated with CD8 level in human UBC tissues, indicating that CD8+ T cell infiltration is closely associated with CCL4 in the hot tumor subtype." (PMID 33777927, 2021). "With this in mind, the higher IL-17 production observed by flow cytometry and expression of the inflammatory genes RSG1, CCL3, and CCL4 revealed by our scRNA-seq data could support a pro-tumorigenic role of CD39 expression in tumor-infiltrating MAIT cells in CRC." (PMID 33205061, 2020). "CCL4 rs10491121 may be a factor to predict the tumor size in OSCC patients." (PMID 28404909, 2017). "Chemokines such as CCL2 and CCL4 could help recruit transferred T cells to the primary tumor site and thereby prevent tumor recurrence, and inflammatory cytokines like IL-6 can promote effector T cell infiltration of distant tumor sites." (PMID 23935927, 2013).
tumor (continued). "This review compiles current knowledge on the significance of lesser-known chemokines in MM tumor processes, including CXCL13, CCR2 ligands (CCL2 [MCP-1], CCL7 [MCP-3]), CCL4, CCL5 (RANTES), CCL17, CCL20, CCL27, CCL28, and CX3CL1 (fractalkine)." (PMID 41749925, 2026). "Here, we analyzed chemokine production and macrophage phenotypes in tumor-affected lymph nodes in EBL, focusing on CCL4." (PMID 42158858, 2026). "Consistent with our Visium analysis, Xenium gene expression analysis revealed that Tfh-like cells located near tumor regions were enriched for C06b CD103+ Tfh-like signature genes, including CCL5, CCL4, GZMA, HAVCR2, and CSF1." (PMID 41542042, 2026). "In a mouse melanoma model, basophils released CCL3 and CCL4, which played a crucial role in attracting CD8+ T cells to the tumor site, thereby promoting tumor rejection." (PMID 40873585, 2025). "CCL4, CXCL8, and MIF have received considerable attention for their roles in tumor proliferation, differentiation, angiogenesis, and tumor progression." (PMID 40092701, 2025). "To learn more about how much cytokine and chemokine levels varied in different tumor compartments depending on the T cell infiltration, we grouped the data of the top four proteins, IL-9, CXCL10, CCL4, and VEGF, median-based into high and low." (PMID 40497965, 2025). "For instance, tumour cells with high FAT2 expression have been reported to upregulate several chemokines that influence immune cell behaviour, including CCL2, CCL3, CCL4, CCL19, CXCL10, and CXCL11." (PMID 40361472, 2025). "In general, chemokines such as CCL2, CCL4, and CXCL10 can recruit cytotoxic T lymphocytes (CTLs) to the tumor and thus promote the anti‐tumor response." (PMID 40145607, 2025). "This insufficient vascularization is often accompanied by low levels of chemokines such as CCL4, CCL5, and CCL20, which are essential for recruiting dendritic cells to the tumor site for effective antigen presentation." (PMID 41149836, 2025). "CCL4, CXCL8, and MIF have been shown to induce angiogenesis and immune escape of tumor cells and promote the progression of many human cancers 10-13." (PMID 40092701, 2025). "Abemaciclib promotes the expression of CCL4 in ovarian cancer animal models by inhibiting SCD1, thereby leading to the infiltration of CD8+ effector T cells into the tumor." (PMID 41463246, 2025). "Some studies have suggested redundant roles for CCL2 and CCL4 so we expected that our CCR2 and CCR5 armored CAR-T cells would be equivalent in terms of in vitro and in vivo tumor-directed homing and efficacy." (PMID 41424784, 2025). "For instance, hyperactivation of the Wnt/β-catenin pathway downregulates chemokines CCL4 and CCL5, impairing DC precursor migration to tumor sites and thereby reducing antigen presentation and T-cell activation." (PMID 41463331, 2025). "The analysis revealed that CCL4 (p = 0.0076) and CCL5 (p = 0.0347) expression levels tended to decrease as the tumor progressed." (PMID 39859340, 2025). "Through DEGs analysis, we observed that CD8+ TEF exhibited higher expression levels of CCL4 and CCL5, both of which facilitate the recruitment of macrophages, dendritic cells, and other T cells into the tumor microenvironment." (PMID 40303328, 2025). "However, studies have also suggested that CCL4/CCL5/CCR5 may play some role in anti‐tumor therapy." (PMID 40145607, 2025). "At the molecular level, transcription factors such as STAT1, CEBPB, HIF1A, and REL, collectively drive MDSCs expansion, while chemokines like CCL3, CCL4, CCL8 and IL1B regulate their migration within the tumor microenvironment." (PMID 41252877, 2025). "It is known that PBMC recruitment plays essential roles in tumor progression and metastasis and that cancer cells are able to recruit them by secreting several chemokines, such as CCL2, CCL3, CCL4, and CCL5 among many others." (PMID 40112045, 2025).
tumor (continued). "On the other hand, CCL4 activates CCR5 of cancer cells to up-regulate the expression of VEGF-C through signaling pathways such as NF-κB, MAPK and PI3K/Akt, driving tumor vascularization." (PMID 41445742, 2025). "Among them, the high expression of CCL4/CCL11/CCL28 is closely related to the prolonged survival period of patients, suggesting its potential for tumor suppression." (PMID 41445742, 2025). "Further analysis showed increased production of proinflammatory interleukins such as IL‐1β and IL‐16 and accumulation of various chemotactic agents, including CCL3, CCL4, CCL5, CXCL9, CXCL10, and CXCL11, in the tumor tissue." (PMID 41221154, 2025). "In the tumor microenvironment, chemokines such as CCL2, CCL3, CCL4, and CCL5 attract monocytes that differentiate into TAMs." (PMID 39941858, 2025). "We reported a significant, higher than in 4T1 tumor-bearing mice, 2’3’-cGAMP-induced increase in CXCL10, CCL2, CCL4, TNF-α, IFN-α and IFN-β concentrations." (PMID 39857957, 2025). "CCL4 and CCL5 are involved in attracting endogenous T cells and monocytes to the tumor site, while GM-CSF mediates the differentiation and activation of APC, as well as activation of T cells." (PMID 38856749, 2024). "PGE2 is directly involved in the complex tumor inflammatory microenvironment, inhibiting inflammatory chemokines CCL3 and CCL4, preventing the accumulation of activated immune cells." (PMID 39450252, 2024). "CCL3 and CCL4 can promote migration of immunosuppressive MDSC and TAMs into the tumor microenvironment (TME) and have been shown to correlate with worsening patient outcomes." (PMID 38108458, 2024). "Some of them, including CCL4, IL10, and THBD, have well-studied mechanisms that contribute to tumor growth promotion." (PMID 38832259, 2024). "It has also been observed that inter-tumoral MDSCs produce high amounts of CCL-3, CCL-4, and CCL-5, which can attract CCR5+ T-regs to the tumor site." (PMID 39609700, 2024). "On the other hand, the other two groups exhibited high expression of CCL4 and SELENOP, both of which have immunosuppressive and tumor-promoting functions." (PMID 38311726, 2024). "In endometrial carcinoma cells, increased levels of CCL4 meant the upregulation of vascular endothelial growth factor-A (VEGF-A) and tumor growth." (PMID 38928238, 2024). "Immunofluorescence staining in tumour-bearing liver from KPC mice and littermate controls confirmed that the CCR5 ligands CCL3, CCL4 and CCL5, and the cytokines IL-12, IL-15 and IL-18 were produced by KCs in peritumoural liver." (PMID 38326607, 2024). "Consistently, quantification of activated natural killer (NK) cells and CD8+ T cells in the metastatic liver showed that they were also preferentially enriched at the tumour margin, next to KCs expressing CCL3, CCL4, CCL5, IL-12, IL-15 and IL-18." (PMID 38326607, 2024). "After binding to CCL4 and its receptor C-C chemokine receptor type 5 (CCR5), it can recruit and mediate immune cell migration, destroy the stability of the tumor microenvironment (TME), participate in carcinogenesis and promote the development of tumors." (PMID 39318254, 2024). "Under the influence of GBM, GAMs are a major source of inflammatory cytokines (e.g., IL-1β, IL-8, IL-10) and chemokines (e.g., CCL2, CCL4, CCL5) that support GBM growth and mitigate anti-tumor immune function." (PMID 37368789, 2023). "The CC chemokines, CCL4 and CCL3, act alone or together by regulating the tumor immune microenvironment to promote tumor progression." (PMID 37745301, 2023). "In turn, the IL9-polarized macrophages secreted chemokines, including CCL3, CCL4, CXCL9, and CXCL10, to recruit antitumor T cells, NKs, DCs, and macrophages to infiltrate the tumor." (PMID 36968220, 2023). "Collectively, CD8 T cell infiltration and exhaustion status, CCL4 and CCR6 expression are different immune components that were affected by the CDKN2A genetic alterations in a way that finally enables tumor growth and progression." (PMID 37626750, 2023).
tumor (continued). "IE1 tumors also had increased scores for chemotactic interactions, mainly mediated by CCL3, CCL4, CCL5, and CXCL9, suggesting a more dynamic immune environment with increased potential for recruitment of cells from outside the tumor." (PMID 36609566, 2023). "We investigated associations of a 4-chemokine expression signature (c-Score: CCL4, CCL5, CXCL9, CXCL10) with metrics of antitumor immunity across tumor types." (PMID 37558751, 2023). "In liver tumors, scRNA-seq analysis identified three pro-tumor TAN subsets (CCL4+ TANs, IFIT1+ TANs, and SPP1+ TANs) and one anti-tumor subset (APOA2+ TANs)." (PMID 38066642, 2023). "Enzyme-linked immunosorbent assay (ELISA) validated that TAMs with Id1 depletion, isolated from CRC patient tumor tissues, MC38-derived tumor tissues or induced from BMDMs, showed increased CCL4 protein abundance." (PMID 37996458, 2023). "By inhibiting β-catenin pharmacologically, it is possible to increase the number of dendritic cells (DCs), upregulate CCL4, and promote the infiltration of CD8+ T cells in various tumor models, including CRC, thereby reactivating anti-tumor immune responses." (PMID 37920463, 2023). "According to recent data, tumor-infiltrating macrophages have been mostly described in those PitNETs with hypersecretion of CCL2, CCL3, CCL4, and IL-8." (PMID 37958702, 2023). "Neutrophil cluster 6 also has high expression of Ccl2, Ccl3, Ccl4, Ccl5, and Cxcl2, which are inflammatory mediators involved in MDSC migration to and activation in the tumor microenvironment." (PMID 37483625, 2023). "Analysis of immune cell number and fraction demonstrated that tumor thrombus had higher myeloid cell infiltration (including neutrophils, TAM-M1, and TAM-M1 with high expression of CCL4), which suggested a relatively immunostimulatory TME in OS tumor thrombus." (PMID 37244923, 2023). "Stimulated leukocytes, fibroblasts, and tumor cells produce CCL3 (MIP-1α) and CCL4 (MIP-1β), which induce chemotaxis of T cells, monocytes, NK cells, and dendritic cells by interacting with their specific receptor CCR5." (PMID 37465147, 2023). "These alterations modulate several immune components, including the infiltration and the exhaustion status of the CD8 T cells in addition to the expression of the chemokine CCL4 and the chemokine receptor CCR6 to finally potentiate the tumor growth." (PMID 37626750, 2023). "Current monoculture tumor spheroid models lack the presence of specific cytokines present in the PDAC TIME, such as CCL4/MIP-1β, CCL5/RANTES, CXCL9, and CXCL10 accidentally simulating an immune silent or excluded PDAC TIME." (PMID 37519820, 2023). "The activation of the Wnt/β-catenin pathway by CTNNB1 mutations contributes to a decline in TIL by inducing downregulation of the chemokines CCL4 and CCL5 that attract dendritic cells and T cells into tumor tissue." (PMID 37190307, 2023). "This decreasing trend was also observed for other chemoattractants important for recruiting immune cells to disrupt tumor growth, specifically MIG (CXCL9), MIP-1ɑ (CCL3), and MIP-1β (CCL4)." (PMID 36968140, 2023). "Our study revealed that the TME endowed TAMs with high ID1 expression, which interacts with STAT1 to inhibit CCL4 and SerpinB2 transcription, two STAT1 target genes, leading to CD8+ T cell exclusion in tumor sites and cancer stemness traits maintenance." (PMID 37996458, 2023). "In the effective treatment group, the expression of inflammation, cytokines, and Toll-receptor-related genes (such as FOS, CCL4, and NR4A2) increased in the CD8+ T cells in tumor tissues after treatment." (PMID 37762493, 2023). "In groups A5, A6, A7, and A8, genes such as CXCL13, HSPA1A, CREM, CCL4, and FOS were highly expressed in CD8+ or CD4+ T cells in tumor tissues." (PMID 37762493, 2023). "Overexpression of EIF4E3 can induce the expression of CCL4/CCL5, playing a significant role in monocyte differentiation in the tumor microenvironment." (PMID 37664112, 2023).